ALDH1B1 (aldehyde dehydrogenase 1 family member B1)
Diseases named in the same sentence as ALDH1B1 in open-access papers (continued):
Sharing a sentence is not in itself a finding about the gene and the disease.
glioma (3 papers, 2021 to 2023). A benign or malignant brain and spinal cord tumor that arises from glial cells (astrocytes, oligodendrocytes, ependymal cells). "Analysis of the TCGA dataset showed that ALDH16A1, ALDH3B1, ALDH1A3, ALDH3A1, ALDH7A1 were significantly increased in IDH wildtype gliomas, while ALDH2, ALDH6A1, ALDH5A1, ALDH1A1, ALDH1L2, ALDH18A1, ALDH1B1 expression were higher in IDH mutant gliomas than IDH wildtype gliomas." (PMID 35116021, 2021).
prostate carcinoma (3 papers, 2017 to 2022). A carcinoma that arises from epithelial cells of the prostate gland. "In a mendelian randomization study, it was found that in ALDH1B1 (rs10973794) was associated with PCa mortality with low-grade prostate cancer (HR = 1.43; p = 0.002)." (PMID 35280985, 2022). "In ALDH1B1, rs10973794 (HRfixed = 1.43; 95%CI:1.14,1.79; p values = 0.002) was associated with prostate cancer mortality in men with low‐grade prostate cancer." (PMID 27643404, 2017). "One SNP in ALDH1B1 also exceeds the Nyholt threshold for association with prostate cancer‐specific survival in low‐grade prostate cancer." (PMID 27643404, 2017). "Another intronic SNP in ALDH1B1 (also close to IGFBPL1) was found to be associated with increased mortality following a diagnosis of low‐grade prostate cancer." (PMID 27643404, 2017).
adenoma (2 papers, 2020 to 2023). A neoplasm arising from the epithelium. "Generating double knockdowns of ALDH1B1 and APC showed that mice with the absence of 1B1 still formed adenoma colorectal tumors; however, the volume was significantly lower compared to the mice with physiological levels of ALDH1B1." (PMID 36676146, 2023).
atherosclerosis (2 papers, 2024 to 2026). A disease characterized by the build-up of fatty material and calcium deposition in the arterial wall resulting in partial or complete occlusion of the arterial lumen. "Although ALDH1B1 is predominantly expressed in the liver, pancreas, and kidney, previous, studies have demonstrated that it is also detectable in arterial and atherosclerotic plaque tissues, where its expression is downregulated during the progression of atherosclerosis." (PMID 41501766, 2026).
liver cancer (2 papers, 2017 to 2020). An epithelial or non-epithelial malignant neoplasm that arises from the liver. "With the cutoff value set at the median or quartile, we determined that ALDH1B1 was the only isoform associated with the clinical outcomes of 360 liver cancer patients in the OncoLnc database." (PMID 28792511, 2017). "The univariate Cox proportional hazard regression model revealed a lower hazard risk in the liver cancer patients with high ALDH1B1 expression levels." (PMID 28792511, 2017). "The high expression of ALDH1B1 correlated with a favorable clinical outcome in liver cancer patients (log–rank, P = 0.0237)." (PMID 28792511, 2017). "From the Oncomine database, we found that ALDH1B1 expression was downregulated in liver cancer tissues compared to that of the normal tissues, which suggested ALDH1B1 as a potential tumor suppressor gene." (PMID 28792511, 2017). "High ALDH1B1 expression was found to play a protective role in liver cancer patients." (PMID 28792511, 2017). "In contrast, downregulation of ALDH1B1 and ALDH1L1 was found in liver cancer compared with normal tissues." (PMID 28792511, 2017).
lung carcinoma (2 papers, 2024 to 2025). "In this study, we performed the in vivo CRISPR loss-of-function screening in lung cancer cells with sgRNA targeting 1685 metabolic enzymes and identified that aldehyde dehydrogenase 1 family member B1 (ALDH1B1) is required for tumor cell survival in confining capillaries." (PMID 41390768, 2025). "High levels of ALDH1B1 expression could be used to identify lung cancer patients who are at higher risk of poor outcomes." (PMID 39408636, 2024). "Given the necessity of ALDH1B1 activity for the survival of the confined cells, we next evaluated the therapeutic potential of ALDH1B1 inhibitor for lung cancer metastasis." (PMID 41390768, 2025). "To delineate the clinical relevance of our finding, we examined the levels of ALDH1B1 or the levels of nuclear RelA in primary tumor tissues from lung cancer patients." (PMID 41390768, 2025). "In lung cancer patients, confined tumor cells exhibit higher levels of ALDH1B1 and NF-κB activation, which correlates with metastatic recurrence." (PMID 41390768, 2025). "In this study, we demonstrate that ALDH1B1 promotes lung cancer metastasis by sustaining tumor cell survival during confined migration." (PMID 41390768, 2025). "Further studies are required to enhance our understanding of the underlying role of ALDH1B1 in the CSC phenotype and its association with lung cancer progression." (PMID 39408636, 2024). "Elevated ALDH1B1 expression suppresses ferroptosis by enhancing aldehydes detoxification in confined cells, which supports tumor cell survival during their migration in confining capillaries, thereby promoting lung cancer metastasis." (PMID 41390768, 2025). "Notably, ALDH1B1 inhibitor IGUANA-1 dampens brain metastasis of lung cancer and markedly extends the lifespan of metastatic tumors-bearing mice." (PMID 41390768, 2025). "Furthermore, immunofluorescence analysis of tumor tissues from lung cancer patients revealed that ALDH1B1 expression was elevated in tumor cells confined within capillaries compared to those outside capillaries, and correlated with metastatic recurrence." (PMID 41390768, 2025). "We demonstrate that ALDH1B1 expression enhances aldehydes detoxification and suppresses ferroptosis in confined cells, which supports tumor cell survival during their migration in confining capillaries, thereby promoting lung cancer metastasis." (PMID 41390768, 2025).
Obesity (2 papers, 2020 to 2022). Accumulation of substantial excess body fat. "Five differentially methylated regions were in genes previously found to be associated with obesity and altered metabolic states (TRAP1, SLC38A3, PROX1, ALDH1B1, and FAM96A)." (PMID 36474183, 2022). "For example, miR-615-3p interacts with CPT1C in obesity and regulates ACOX1 and ALDH1B1 in uterine cancer." (PMID 33121472, 2020).
ovarian carcinoma (2 papers, 2019 to 2023). A malignant neoplasm originating from the surface ovarian epithelium. "ALDH1A2, ALDH1B1, and ALDH9A1 were downregulated in the ovarian cancer cells compared to the expression in HOSE cells, whereas ALDH3A1 was upregulated in the ovarian cancer cells." (PMID 31615043, 2019).
alcohol dependence (1 paper, 2017). Physical and psychological dependence on alcohol. "However, other genes, for example ALDH1B1, have the capacity to oxidize acetaldehyde at physiologically relevant rates and may be of importance in relation to alcohol dependence in European populations." (PMID 28594837, 2017).
arrhythmogenic right ventricular cardiomyopathy (1 paper, 2025). "High expression of ALDH1B1 was enriched in arrhythmogenic right ventricular cardiomyopathy, whereas low expression was enriched in the allograft rejection pathway." (PMID 40441253, 2025).
colonic adenomas (1 paper, 2023).
diffuse gastric adenocarcinoma (1 paper, 2016). An adenocarcinoma arising from the stomach. "As another good predictor, high level of ALDH1B1 predicted better OS in gastric intestinal type adenocarcinoma, with HR = 0.57 (0.41–0.78), p = 0.0000 and worse OS in diffuse gastric adenocarcinoma, with HR = 1.92 (1.46–2.51), p = 0.0000." (PMID 27015121, 2016). "However, in Kaplan-Meier plotter analysis, the ALDH1B1 in this study was found to be a good prognostic marker for OS in patients with all types of GC and intestinal type gastric adenocarcinoma, a poor prognostic marker for OS in patients with diffuse gastric adenocarcinoma." (PMID 27015121, 2016).
endometriosis (1 paper, 2024). The growth of functional endometrial tissue in anatomic sites outside the uterine body. "Aldehyde dehydrogenase 1 family member B1 (ALDH1B1) was also significantly decreased in endometriosis relative to normal decreased across all time points." (PMID 38402336, 2024).
esophageal cancer (1 paper, 2024). A primary or metastatic malignant neoplasm involving the esophagus. "In the unstratified analysis, all variants except ALDH1B1 rs2228093 and GOT2 rs73550818 showed significant associations (P < 0.05/8 = 0.00625) with esophageal cancer risk." (PMID 38277453, 2024).
intestinal tumour (1 paper, 2023). "We hypothesised that widespread loss of ALDH1B1 further increases acetaldehyde levels, causing more acetaldehyde-mediated DNA damage, which may interact with defective MMR to enhance intestinal tumour formation." (PMID 37395714, 2023).
liver fibrosis (1 paper, 2017). "Furthermore, it also suggested that the alteration of ALDH1B1, ALDH2 and ALDH7A1 levels may be potential biomarkers for the curative effect evaluation of gypenoside against liver fibrosis." (PMID 28291813, 2017).
lung adenocarcinoma (1 paper, 2024). A carcinoma that arises from the lung and is characterized by the presence of malignant glandular epithelial cells. "Concurrently, ALDH1B1 was found to be associated with lung tumorigenesis, as evidenced by its enhanced transcriptional expression levels in TCGA lung adenocarcinoma clinical samples compared to normal lung tissue." (PMID 39408636, 2024). "In light of the association between ALDH1B1-mediated lung tumor formation, chemoresistance and CSC phenotype, our study focused on elucidating the contribution of ALDH1B1 to the pathophysiological mechanisms underlying human lung adenocarcinoma." (PMID 39408636, 2024). "This study examines the potential role of ALDH1B1 in human lung adenocarcinoma and its association with the CSC phenotype." (PMID 39408636, 2024). "Our research contributes to our understanding of the role of ALDH1B1 in malignancies, highlighting its potential as an important biomarker in human lung adenocarcinoma." (PMID 39408636, 2024). "To this end, we utilized the lung adenocarcinoma cell line A549, engineered to stably express the human ALDH1B1 protein tagged with green fluorescent protein (GFP)." (PMID 39408636, 2024). "The main aim of our study was to elucidate the role of ALDH1B1 in human lung adenocarcinoma." (PMID 39408636, 2024). "Moreover, the relative expression levels of ALDH1B1 were higher in lung adenocarcinoma TCGA samples compared to normal tissue." (PMID 39408636, 2024). "Combining ALDH1B1 inhibition with other therapies, such as chemotherapy, targeted therapies, or immunotherapies, could offer more effective strategies for lung adenocarcinoma in the future; however, these strategies require further exploration." (PMID 39408636, 2024). "Next, we further confirmed the ALDH1B1 correlation with CSC-related molecules, depicted by Spearman’s rho in the 507 TCGA clinical lung adenocarcinoma specimens in vitro, using the A549 isogenic cell line pair." (PMID 39408636, 2024). "ALDH1B1 was shown to be statistically significantly correlated with many molecules involved in CSC-related pathways, as analyzed in 507 lung adenocarcinoma clinical data derived from TCGA." (PMID 39408636, 2024). "Finally, the correlation of ALDH1B1 with molecules involved in CSC-related pathways (Wnt, Notch, PI3K/Akt, Hedgehog, retinoic acid, Hippo, NF-κΒ, TGF-β, glycolysis/gluconeogenesis) was confirmed by analyzing lung adenocarcinoma clinical specimens obtained by TCGA." (PMID 39408636, 2024).
pancreatic (1 paper, 2023). "ALDH1B1 expression was also positively correlated with the expression of KRAS, an oncogene implicated in pancreatic carcinogenesis, and the expression of ALDH1B1 was necessary for tumor development in a Kras-induced pancreatic mouse model." (PMID 36676146, 2023).
pancreatic adenocarcinoma (1 paper, 2018). "It has been confirmed that ALDH1B1 was up-regulated in several cancers such as colorectal cancer, pancreatic adenocarcinoma, non-small-cell lung cancer and gastric cancer, and it is identified to be involved in tumorigenesis and metastasis." (PMID 29416787, 2018). "In pancreatic adenocarcinoma, ALDH1B1 is over-expressed and may be an critical modulator of tumor progression." (PMID 29416787, 2018).
pancreatic ductal adenocarcinoma (1 paper, 2022). An infiltrating adenocarcinoma that arises from the epithelial cells of the pancreas. "Upregulation of ALDH1B1 by Kras is associated with pancreatic lineage homeostasis and initiation/development of pancreatic ductal adenocarcinoma, which are characteristics of enhanced production of reactive oxygen species by altering mitochondrial metabolism." (PMID 35280765, 2022).
psoriasis (1 paper, 2017). An autoimmune condition characterized by red, well-delineated plaques with silvery scales that are usually on the extensor surfaces and scalp. "Only B6 mice, for example, showed significantly decreased expression of Fcer2, Cspg4, Lsp1, and Aldh1b1 with IMQ treatment to recapitulate expression shifts unique to psoriasis lesions." (PMID 28279190, 2017).
rectal adenocarcinoma (1 paper, 2022). "In 531 patients with colon or rectal adenocarcinoma, RNA-seq results indicated that ALDH1B1 exhibits a substantial correlation with DNA repair genes." (PMID 35805102, 2022). "Bioinformatics analysis of 531 colon and rectal adenocarcinoma patient samples validated that ALDH1B1 is statistically significantly positively correlated with the upregulation of various DDS-related proteins." (PMID 35805102, 2022). "Finally, the ALDH1B1 correlation with DDR-associated molecules, which are involved in base excision repair, nucleotide excision repair and NHEJ, was confirmed by analyzing colon and rectal adenocarcinoma patient samples obtained by TCGA." (PMID 35805102, 2022). "Furthermore, the expression of ALDH1B1 triggered altered profiles of various DDS-related genes, which was further validated by analyzing 531 publicly available colon and rectal adenocarcinoma clinical samples." (PMID 35805102, 2022).
thyroid cancer (1 paper, 2022). "In this study, high ALDH1B1 expression in thyroid cancer was associated with poor OS in male patients, suggesting a correlation between ALDH1B1 and androgen." (PMID 35280765, 2022). "Our results showed that the transcriptional levels of ALDH1A1 and ALDH1B1 significantly decreased in thyroid cancer tissues, whereas that of ALDH1A3 increased." (PMID 35280765, 2022). "We observed that the regulatory functions of ALDH1A1 and ALDH1B1 in thyroid cancer were involved in poor outcome in patients and inhibition of TILs." (PMID 35280765, 2022). "MRNA expressions of ALDH1A1 and ALDH1B1 significantly decreased in thyroid cancer tissues compared to that in normal groups based on individual cancer stages, gender, tumor histology, and nodal metastasis." (PMID 35280765, 2022). "Interestingly, the expressions of ALDH1A1 and ALDH1B1 were higher in the normal thyroid tissues and decreased in the thyroid cancer tissues." (PMID 35280765, 2022). "And high levels of ALDH1B1 also impaired OS in patients with thyroid cancer." (PMID 35280765, 2022). "Therefore, androgen receptor expression may be involved in ALDH1B1-induced thyroid cancer progression." (PMID 35280765, 2022). "Furthermore, immunohistochemical results verified that ALDH1A1, ALDH1A3, and ALDH1B1 were highly expressed in thyroid cancer at the protein level, suggesting the role of ALDH1A1/A3/B1 in thyroid cancer development." (PMID 35280765, 2022).
cancer (33 papers, 2015 to 2025). A tumor composed of atypical neoplastic, often pleomorphic cells that invade other tissues. "ALDH1B1 has been identified as a biomarker for colorectal cancer and has been linked to cancer stem-like features." (PMID 39408636, 2024). "TRAF6 also suppresses CSC properties by conjugating K27- and K33-linked ubiquitination to the cancer stemness marker aldehyde dehydrogenase 1 family member B1 (ALDH1B1) and decreasing its enzyme activity." (PMID 38104139, 2023). "Its great importance is highlighted by the multiple pathological conditions, both cancer and non-cancer related, with which ALDH1B1 has been associated over the years." (PMID 36676146, 2023). "ALDH1B1 is considered a valid marker of colon carcinogenesis and cancer stem-like phenotype, but it also appears to be associated with normal colon stem cells." (PMID 36676146, 2023). "ALDH1B1 has been associated with survival in several different types of cancer, leading to contradictory results." (PMID 36676146, 2023). "ALDH1B1 is overexpressed in various cancers and is tightly associated with tumorigenesis and therapy resistance." (PMID 36545122, 2022). "Further investigation is required to enhance our understanding on the underlined role of ALDH1B1 in DNA damage response and repair and its relation with cancer progression." (PMID 35805102, 2022). "Overall, our findings enhance our understanding on the underlined role of ALDH1B1 in cancer progression." (PMID 33419031, 2021). "The expression of aldehyde hydrogenase ALDH1B1 gene, which is involved in RA biosynthesis and associated with cancer cell stemness, was induced by RA in the control cells but not in the CRABP1-depleted cells." (PMID 26142905, 2015). "While ALDH1B1 may indirectly or loosely support a rad-age association, given its ties to cancer progression and radioresistence, this enzyme also perks our interest once more on being yet another metabolic constituent." (PMID 38584916, 2024). "Additional, ALDH1B1, an alcohol metabolism associated enzyme located in mitochondrial, may affect cellular metabolism by which facilitate survival of cancer cells." (PMID 29416787, 2018). "Unlike ALDH3A2, aldehyde dehydrogenase 1 family member A1 (ALDH1A1), 1 family member B1 (ALDH1B1), and 3 family member A1 (ALDH3A1) expression levels are elevated in other malignant tumors and associated with poorer survival outcomes." (PMID 40923024, 2025). "Our finding reveals the critical role of ALDH1B1 in cancer metastasis and demonstrates the regulatory mechanism of ALDH1B1 expression upon mechanical compression and implicates the therapeutic potential of ALDH1B1 inhibitor to treat metastatic lung cancer." (PMID 41390768, 2025). "Subsequently, we investigated the association between ALDH1B1 gene expression and the expression of CSC-related molecules using data from 507 clinical cancer samples data downloaded from the TCGA database." (PMID 39408636, 2024). "ALDH1B1 is upregulated in several cancers, such as colorectal and pancreatic cancers, and acts as an oncogene." (PMID 36831600, 2023). "In the following section, we will discuss ALDH1B1′s role in the development of cancer and the CSC phenotype." (PMID 36676146, 2023). "Among four AcAH metabolizing enzymes, upregulation of ALDH1A1 and ALDH1B1 have been reported in various cancers." (PMID 36831600, 2023). "Further research using large prospective patient cohorts are warranted to determine the prognostic value of ALDH1B1 in certain cancers." (PMID 36694633, 2023). "Here, we review the basic concepts related to CSCs and discuss the potential role of ALDH1B1 in cancer development and its contribution to the CSC phenotype." (PMID 36676146, 2023). "Five hypermethylated regions were in genes previously associated with cancer (TRAP1, SLC38A3, CHRM1, EDN2, and PROX1), while six hypomethylated regions were in genes previously associated with cancer (NUMBL, ALDH1B1, FTCD, FASTKD2, FAM96A, and ARHGAP15)." (PMID 36474183, 2022).